MFN2 (mitofusin 2)
Diseases named in the same sentence as MFN2 in open-access papers (continued):
Sharing a sentence is not in itself a finding about the gene and the disease.
Charcot-Marie-Tooth disease type 2A (continued). "Charcot-Marie-Tooth disease type 2A (CMT2A), an untreatable neurodegenerative condition, can result from varying dominant hereditary mutations in MFN2." (PMID 36556475, 2022). "Phenotypic variations in Charcot-Marie-Tooth disease type 2A (CMT2A) result from the many mutations in the mitochondrial fusion protein, mitofusin 2 (MFN2)." (PMID 36556475, 2022). "Mutations in MFN2 (most commonly autosomal dominant) cause Charcot-Marie-Tooth disease type 2A (CMT2A), the commonest axonal form of CMT, with significant allelic heterogeneity." (PMID 33415332, 2020). "Charcot-Marie-Tooth disease type 2A (CMT2A) is an autosomal dominant axonal peripheral neuropathy caused by mutations in the mitofusin 2 gene (MFN2) [MIM: 608507]." (PMID 30442897, 2018). "Interestingly, mutations in fusion components are linked to neurodegenerative disorders with Opa1 mutations causative for dominant optic atrophy and mutations in Mfn2 linked to Charcot-Marie-Tooth type 2A disease, a peripheral neuropathy sometimes accompanied by optic degeneration and hearing loss." (PMID 23285122, 2012). "Optic nerve involvement is also seen in other mitochondrial neurodegenerative conditions, such as Friedreich’s ataxia (FXN) or Charcot-Marie-Tooth disease type 2A (MFN2)." (PMID 41149856, 2025). "We focused on the outer mitochondrial membrane (OMM) protein mitofusin 2 (MFN2), because its ablation impairs OXPHOS and mutations in MFN2 in humans are associated with lipodystrophies and an axonal neuropathy known as Charcot-Marie-Tooth Disease type 2A." (PMID 39433901, 2024). "The importance of mitochondrial fusion to human health is underscored by the findings that mutations in the mitochondrial fusion machinery components Mfn2 and OPA1 cause Charcot-Marie-Tooth disease type 2A and autosomal dominant optic atrophy, respectively." (PMID 28924745, 2018). "An expanding number of degenerative disorders are associated with mutations in the genes encoding MFN2 and OPA1, including Charcot-Marie-Tooth disease type 2A and autosomal dominant optic atrophy." (PMID 23781337, 2013). "Mutations in MFN2 and OPA1 are associated with human neuropathies, such as Charcot-Marie-Tooth disease type 2A (CMT2A) and dominant optic atrophy (DOA), respectively." (PMID 24957874, 2011). "One of the most common inherited axonal neuropathies, Charcot-Marie-Tooth disease type 2A (CMT2A), is caused by dominant mutations in MFN2 (Mitofusin 2 deficiency), classified by the ICIMD under group 19 (Disorders of organelle biogenesis, dynamics, and interactions)." (PMID 41517394, 2025). "Mutations in the optic atrophy 1 (OPAI) or Mitofusin 2 (MFN2) genes, which represent two mitochondrial dynamic regulators, lead to an impaired mitochondrial function and contribute to optic atrophy or charcot-marie-tooth disease type 2A (a familial neuropathy)." (PMID 39871928, 2022). "Strikingly, mutations in MFN2 but not MFN1 can cause Charcot-Marie-Tooth disease type 2A (CMT2A), a peripheral neuropathy characterized by axonal degeneration." (PMID 32595603, 2020). "Disruptions in these processes, often caused by MFN2 or OPA1 mutations, are linked to neurodegenerative diseases like Charcot-Marie-Tooth disease type 2A (CMT2A) and autosomal dominant optic atrophy (ADOA)." (PMID 40149969, 2025). "We describe a family carrying a novel MFN2 mutation associated with ALS-frontotemporal dementia (FTD) clinical phenotype in the mother and Charcot-Marie-Tooth disease type 2A (CMT2A) in her son." (PMID 37547466, 2023).
heart failure (34 papers, 2015 to 2026). Inability of the heart to pump blood at an adequate rate to meet tissue metabolic requirements. "MFN2 has been implicated in various CVDs, including I/R injury, heart failure, and dilated cardiomyopathy." (PMID 40520935, 2025). "Dysfunction of MFN2, a key protein involved in forming and regulating MAMs, has long been associated with CVDs, including heart failure." (PMID 40520935, 2025). "A report from Dorn’s group exhibits that hearts deficient in Mfn1 and Mfn2 contribute to progressive dilated cardiomyopathy at five weeks and heart failure from seven to eight weeks." (PMID 34026850, 2021). "The ablation of MFN2 in hearts also leads to impaired Parkin-mediated mitophagy causing an accumulation of damaged ROS-producing organelles and progressive heart failure." (PMID 25987420, 2015). "Besides, autophagosome–lysosome fusion is impaired in Mfn2-deficient mice, leading to accumulation of autophagosomes and progressive heart failure." (PMID 34026850, 2021). "While these findings highlight the role of MFN2 in heart failure, relevant reports remain scarce, indicating the need for further research to uncover the specific mechanisms involved." (PMID 40520935, 2025). "Ketone bodies are beneficial for mitochondrial repair in aging hearts; however, in heart failure, MFN2 and DRP1 expression is reduced by nearly 50%, impairing the fusion–fission process; thus, ketone bodies reduce mitophagy." (PMID 39125651, 2024). "Reduced expression of the fusion proteins Mfn2 and Opa1 was also observed in vitro in hypertrophic cardiomyocytes and a rat model of heart failure." (PMID 36860274, 2023). "It has been reported that cardiac deficiency of Mfn1 and Mfn2 exhibits progressive DCM and heart failure in succession." (PMID 36776252, 2023). "A study showed that MFN1/MFN2 double knockout mice died at the embryonic stage due to heart failure." (PMID 36776252, 2023). "Preventing mitochondrial fragmentation by reconstructing Mfn2 protects against cell death and heart failure." (PMID 37106782, 2023). "Intriguingly, cardiac‐specific MFN1‐ or MFN2‐knockout mice develop normally, although cardiac‐specific deletion of MFN1–MFN2 causes rapid heart failure and premature death in mice." (PMID 38156294, 2023). "Accumulating studies have demonstrated that MFN2 was downregulated in heart failure models induced by spontaneously hypertensive rats (SHR) or TAC." (PMID 36776252, 2023). "The upregulation of Drp1 and Mfn2 in heart failure is in accordance with our previous study analyzing human diaphragm samples from HF patients." (PMID 36232292, 2022). "Here, this review mainly focuses on what is known about the structure and function of Mfn2 and its crucial role in heart failure." (PMID 34026850, 2021). "In this review, we focus on the current understanding of Mfn2 structure, function, and its role in heart failure." (PMID 34026850, 2021). "Mfn2 dysfunctions have been found to contribute to cardiovascular diseases, such as ischemia-reperfusion injury, heart failure, and dilated cardiomyopathy." (PMID 34026850, 2021). "Although, direct modulation of Mfn1 and Mfn2 by the sex hormones is still unclear in heart failure, several studies have indicated estrogen and testosterone are cardioprotective factors." (PMID 34026850, 2021). "The disruption of Mfn2-mediated intact ER-mitochondrial contacts exists in conditions of heart failure induced by transverse aortic constriction (TAC), which is associated with a decreased excitability and force generation in cardiac myocytes." (PMID 31379586, 2019). "The potential for activation of Mfn‐2 as a therapeutic strategy for cardioprotection in ischaemic disease and heart failure has recently received considerable attention." (PMID 28261787, 2017). "Combined Mfn1 and Mfn2 ablation in mouse hearts resulted in accumulation of dysfunctional and fragmented mitochondria and led to lethal heart failure at approximately 8 weeks after Mfn1/Mfn2 ablation." (PMID 25652199, 2015).
heart failure (continued). "This suggests that the elevated levels of MFN1 and MFN2 observed in the failing heart may result from impaired proteasome activity, consistent with findings from animal models of heart failure and human cardiac failure." (PMID 40520935, 2025). "On one hand, Mfn2 deletion has been reported to protect against ischemia–reperfusion injury, but on the other, it may lead to cardiac hypertrophy and heart failure." (PMID 41294815, 2025). "Furthermore, Mfn1/Mfn2 double-KO mice develop heart failure during embryonic life, leading to death." (PMID 40520935, 2025). "In addition, a reduced ratio of Mfn2 to Drp1 was observed in heart failure, while Mdivi-1 treatment normalized this ratio and thus improved cardiac function." (PMID 36860274, 2023). "Combined ablation of Mfn1and Mfn2 in mice leads to lethal heart failure." (PMID 39077079, 2023). "MFN2 could regulate heart failure-related mitophagy by altering the mitochondrial membrane potential." (PMID 33062700, 2020). "We discuss how MFN2-mediated MAMs may contribute to the protection against various CVDs, including myocardial ischemia/reperfusion injury, diabetic cardiomyopathy, dilated cardiomyopathy, pathological myocardial hypertrophy, cardiotoxicity, and heart failure." (PMID 40520935, 2025). "Notably, Mfn2 expression has been shown to decrease during the development of heart failure." (PMID 38865270, 2024). "Western blotting results showed that the expressions of MFN2 and OPA1 proteins were down-regulated in the heart failure group, and up-regulated by aerobic exercise and SKQ1." (PMID 40076760, 2025). "In studies on rats, miR-17-5p has been identified as a key factor promoting pathological myocardial hypertrophy, inhibiting Mfn2 expression, activating the PI3K/AKT/mTOR pathway, and inhibiting autophagy, which leads to heart failure." (PMID 38892295, 2024). "Another study demonstrated that Mfn2 and OPA1 levels are reduced, while DRP1 and FIS1 levels are elevated in heart failure in dogs and humans." (PMID 37371979, 2023). "Compared with donorsamples from normal people, the expression of Mfn2 and OPA-1 in the leftventricular myocardium of patients with heart failure was significantlyup-regulated, while the expression of Drp-1 and fission-1 protein wasdown-regulated." (PMID 39077079, 2023). "Our observations were corroborated by recent data confirming the ability of MitoQ to increase Mitofusin-2 expression in C2C12 cells, as well as in the myocardial muscle during heart failure." (PMID 35392166, 2022). "In this study, although the expression of Parkin was increased in mice with heart failure, MFN2 expression did not change significantly, suggesting that the mitochondrial translocation of Parkin was reduced and mitochondrial autophagy was inhibited." (PMID 40076760, 2025). "We have found that MFN2-mediated MAMs may play significant roles in a variety of CVDs, including MIRI, DCM, pathological myocardial hypertrophy, cardiotoxicity, and heart failure." (PMID 40520935, 2025). "Mfn2 as the central player of the Charcot Marie tooth disease, also participated in the onset and development of various heart diseases, including transverse aortic constriction (TAC), induced heart failure, and myocardial infarction (MI)." (PMID 34026850, 2021). "Conditional deletion of Mfn2 only leads to mild myocyte hypertrophy accompanied by mild deterioration of left ventricular function and does not develop heart failure." (PMID 34026850, 2021). "βIIPKC inhibition by βIIV5-3 selectively re-established cardiac Mfn1 levels and activity in heart failure, without affecting the level or activity of mitofusin 2 (Mfn2)." (PMID 30659190, 2019). "Similarly to MFN2, the disruption of the complex by inhibition of IP3R not only can protect cardiomyocytes against ischemia–reperfusion mediated by cyclophilin D but also decrease myocardial injury and heart failure mediated by less Ca2+ transference between SR to mitochondria." (PMID 41294815, 2025).
autosomal dominant optic atrophy (33 papers, 2008 to 2025). An autosomal dominant hereditary condition characterized by optic atrophy and progressive visual loss. "Mutations in genes of fusion essential proteins, OPA1 and Mfn2, have been associated with two neurodegenerative diseases, autosomal dominant optic atrophy (ADOA) and CMT type 2A, respectively." (PMID 32455165, 2020). "Mutations in some mitochondrial genes have been demonstrated to be the main causes of these metabolic diseases, such as Charcot–Marie–Tooth disease (Mfn2 mutation) and dominant optic atrophy (Opa1 mutation)." (PMID 31551926, 2019). "For example, several missense mutations of MFN2 causing autosomal dominant optic atrophy ‘plus’ phenotype induce a respiratory chain defect and mtDNA deletions and eventually mtDNA depletion in muscle cells." (PMID 28376083, 2017). "Mutations in the fusion genes OPA1 and MFN2 have been associated with dominant optic atrophy and CMT Type 2A, respectively, but the reasons for these genotype–phenotype correlations have remained an enduring mystery." (PMID 27390132, 2016). "Recently, mutations in OPA1 and MFN2 have been described in patients with autosomal dominant optic atrophy (ADOA) and multisystem clinical involvement (including progressive external ophthalmoplegia (PEO)) who harbored mitochondrial DNA (mtDNA) deletions in skeletal muscle." (PMID 23781337, 2013). "Furthermore, in humans, impaired mitochondrial fusion caused by mutations in Opa1 and Mfn2 are associated with dominant optic atrophy or Charcot-Marie-Tooth disease 2A (CMT2A), respectively." (PMID 23285122, 2012). "Mutations in OPA1 and MFN2 genes cause autosomal dominant optic atrophy (DOA); mutations in WFS1 and CISD2 can cause Wolfram syndrome, while Leber's hereditary optic neuropathy (LHON) is associated with mutations in mitochondrial ND1, ND4, and ND6 genes." (PMID 32352005, 2020). "Specifically, MFN2 mutations are linked to Charcot-Marie-Tooth disease (CMT) and OPA1 mutations are associated with autosomal dominant optic atrophy (ADOA)." (PMID 41146909, 2025). "Certain neuropathies, for example, are caused by mutations in Opa1 (autosomal dominant optic atrophy, ADOA) and Mfn2 (Charcot-Marie-Tooth disease type 2A, CMT2A), where patient cells have clear mitochondrial morphology imbalance and dysfunction." (PMID 34698563, 2022). "Gene mutations necessary for mitochondrial fusion, such as OPA1 or Mfn2, can affect multiple tissues, leading to diseases such as autosomal dominant optic atrophy (DOA) and Charot-Marie-Tooth type 2A (CMT2A) respectively." (PMID 35501558, 2022). "In humans, loss of function mutations in MFN2 and OPA1 genes cause the neurodegenerative diseases, Charcot–Marie–Tooth type 2A (CMT2A) and dominant optic atrophy (DOA), respectively." (PMID 33374852, 2020). "These range from the inability to survive past mid-gestation in MFN1, MFN2, OPA1, or DRP-1 deficient mice, to neurodegenerative diseases such as Charcot-Marie-Tooth syndrome and dominant optic atrophy caused by mutations in MFN2 and OPA1." (PMID 31225513, 2019). "Mutations in two mitochondrial fusion genes (MFN2 and OPA1) cause neurodegenerative diseases, namely Charcot-Marie Tooth type 2A and autosomal dominant optic atrophy (ADOA)." (PMID 26113818, 2015). "For example, several neurological diseases (e.g. Charcot-Marie-Tooth, CMT; autosomal dominant optic atrophy, DOA) are associated with mutations in proteins that control mitochondrial dynamics and morphology like mitofusin-2 and OPA1." (PMID 18713454, 2008). "Mitochondrial dynamics are represented by mitochondrial fission processes controlled by mitofusin 1 (MFN1), MFN2, OPA1 (a gene encoding a dynamin-like mitochondrial GTPase involved in autosomal dominant optic atrophy) and fusion processes regulated by dynamic-related protein 1 (DRP1)." (PMID 37762322, 2023).
autosomal dominant optic atrophy (continued). "Of note, germline mutations in Mfn2 cause Charcot–Marie–Tooth hereditary-like neuropathy type 2A (CMT2A), while germline mutations in OPA1 causes the autosomal dominant optic atrophy (ADOA) which is the most common genetic cause of optic atrophy in humans." (PMID 29503614, 2018). "Neurodegenerative diseases such as Charcot–Marie–Tooth 2A (CMT2A) and dominant optic atrophy (DOA) manifest with degeneration of sensory and motor nerves and optic nerve as a direct consequence of mutations in genes encoding mitochondrial fusion proteins Mfn2 and OPA1, respectively." (PMID 26921061, 2016). "Mutations in Mfn2 cause the Charcot-Marie-Tooth type 2A (CMT2A), one of the most common hereditary neuropathies, and mutations in OPA1 are the predominant cause of autosomal dominant optic atrophy (DOA), a heritable form of optic neuropathy." (PMID 22848813, 2012). "Mutations in Mfn2 cause Charcot-Marie-Tooth type 2A (CMT2A), a peripheral neuropathy affecting sensory and motor neurons, while mutations in OPA1 are the primary cause of autosomal dominant optic atrophy (DOA), a degeneration of retinal ganglia cells that results in atrophy of the optic nerve." (PMID 26903809, 2016).